TRAF7 (TNF receptor associated factor 7)
Description:
E3 ubiquitin and SUMO-protein ligase that plays a role in different biological processes such as innate immunity, inflammation or apoptosis. Potentiates MAP3K3-mediated activation of JUN/AP1 and DDIT3 transcriptional regulators. Negatively regulates MYB transcriptional activity by sequestering it to the cytosol via SUMOylation (By similarity). Plays a role in the phosphorylation of MAPK1 and/or MAPK3, probably via its interaction with MAP3K3. Negatively regulates RLR-mediated innate immunity by promoting 'Lys-48'-linked ubiquitination of TBK1 through its RING domain to inhibit the cellular antiviral response. Promotes 'Lys-29'-linked polyubiquitination of NEMO/IKBKG and RELA leading to targeting these two proteins to lysosomal degradative pathways, reducing the transcriptional activity of NF-kappa-B.
Synonyms: RFWD1; RNF119; DKFZp586I021; MGC7807; CAFDADD
Tractability: Antibody: its Gene Ontology location is reachable by antibodies, with high confidence. PROTAC: UniProt records ubiquitination sites on it; ubiquitination databases record sites on it.
Gene: Protein-coding gene on chromosome 16 (2,155,692 to 2,178,129, forward strand). Ensembl gene ENSG00000131653.
Subcellular location: Cytoplasmic vesicle; Cytoplasm; Nucleus
Subcellular location (Human Protein Atlas): Vesicles
Pathways (Reactome):
Cell-Cell communication: Activation of STAT3 by cadherin engagement
Immune System: Antigen processing: Ubiquitination & Proteasome degradation
Gene Ontology:
Molecular function: protein binding; ubiquitin protein ligase activity; ubiquitin-protein transferase activity; zinc ion binding
Biological process: apoptotic process; positive regulation of apoptotic signaling pathway; positive regulation of MAPK cascade; positive regulation of ubiquitin-dependent protein catabolic process; protein K29-linked ubiquitination; protein ubiquitination; regulation of ERK1 and ERK2 cascade; positive regulation of neuron apoptotic process; positive regulation of protein metabolic process
Cellular component: cytoplasm; cytoplasmic vesicle; nucleus; ubiquitin ligase complex
Genetic constraint (gnomAD): Loss-of-function variants: 45 observed, 85.41 expected, observed/expected ratio (o/e) 0.53, 90% interval 0.41 to 0.68. The upper end of that interval is the gene's LOEUF score, 0.68, which puts it in group 2 of 6, group 1 being the genes least tolerant of losing a copy. Missense variants: 677 observed, 906.84 expected, observed/expected ratio (o/e) 0.75, 90% interval 0.7 to 0.8. Synonymous variants: 406 observed, 362.31 expected, observed/expected ratio (o/e) 1.12, 90% interval 1.03 to 1.22.
Gene-disease validity (ClinGen):
ClinGen rates the evidence that TRAF7 causes each of these diseases.
syndromic complex neurodevelopmental disorder (autosomal dominant): Definitive. A disorder that involves more than one phenotype associated with the central nervous system, including but not limited to intellectual disability, autism, and seizures (epilepsy), and also a distinctive pattern of other features including dysmorphisms and/or congenital malformations.
Cancer hallmarks: escaping programmed cell death (suppresses)
Homologues: Orthologues: chimpanzee TRAF7 (99% identical), macaque TRAF7 (99% identical), dog TRAF7 (98% identical), guinea pig TRAF7 (97% identical), pig TRAF7 (97% identical), rat Traf7 (97% identical), mouse Traf7 (97% identical), tropical clawed frog traf7 (92% identical), zebrafish traf7 (87% identical). Paralogues in human: FBXW7 (19% identical), WDR49 (16% identical), EFCAB8 (14% identical), BTRC (14% identical), FBXW11 (14% identical), WDR64 (13% identical), WDR86 (11% identical), FBXW8 (10% identical), FBXW9 (10% identical), PAAF1 (8% identical), FBXW12 (7% identical), WDR54 (7% identical), and 2 more.
Diseases named in the same sentence as TRAF7 in open-access papers:
TRAF7 is named in the same sentence as 68 diseases in open-access papers, as found by Europe PMC text mining. Sharing a sentence is not in itself a finding about the gene and the disease. The quoted sentences say what the papers report.
meningioma (123 papers, 2013 to 2025). A generally slow growing tumor attached to the dura mater. "Separate clustering of NF2- and TRAF7-mutated meningiomas has recently been documented in a large patient cohort." (PMID 41154381, 2025). "Key genetic drivers, including mutations in NF2, SMO, KLF4, TRAF7, and chromosomal aberrations, allow for the stratification of meningiomas into distinct molecular subtypes, each associated with unique clinical outcomes and therapeutic vulnerabilities." (PMID 39941893, 2025). "TRAF7 somatic mutations are most thoroughly studied in meningiomas, tumors arising from the meninges covering the brain." (PMID 41372821, 2025). "In our study, we analysed the most common driver mutations (NF2, AKT1, KLF4, and TRAF7) in meningioma by genomics describing co-occurrences and new mutations." (PMID 40562609, 2025). "Firstly, mutations in the WD40 domain of the TRAF7 impair its interactions with Ras GTPases in the majority of meningiomas." (PMID 41372821, 2025). "Overall, Ras/MAPK signaling activation due to TRAF7 deficiency leads to anchorage-independent growth of meningiomas." (PMID 41372821, 2025). "Numerous studies have reported that TRAF7 mutations are frequently found alongside KLF4 mutations in meningiomas." (PMID 40181456, 2025). "Histological subtype–specific mutations, such as KLF4/TRAF7 in secretory meningiomas and SMARCE1 in clear cell meningiomas, were also not supported by our assay." (PMID 40951339, 2025). "Somatic TRAF7 mutations are associated with subsets of meningiomas, mesotheliomas, and perineuriomas." (PMID 41372821, 2025). "We focus here on the importance of TRAF7 somatic mutations in meningioma molecular biology, which is well-studied, and outline the importance of TRAF7 as a biomarker in mesothelioma, perineurioma, and adenomatoid tumors." (PMID 41372821, 2025). "Anterior parasagittal meningiomas are often driven by TRAF7, KLF4, or SMO mutations, while posterior ones are typically NF2-driven." (PMID 40569492, 2025). "One particularly striking effort in interrogating the underlying pathological genetic variants in SB meningioma has been the implication of TRAF7 dysfunction." (PMID 40867323, 2025). "Mutations in TRAF7 are the second most common alteration in meningioma, which are found in 25% of tumors." (PMID 41372821, 2025). "In some instances TRAF7 can act as a tumor suppressor gene and loss of function mutations precipitate cancer development (meningiomas)." (PMID 41372821, 2025). "In the study of meningioma, TRAF7 deficiency activated the RAS/MAPK pathway and promoted the tumor progression." (PMID 40181456, 2025). "Multiple next-generation sequencing technologies studies have identified somatic TRAF7 driver mutations in anterior SB meningiomas." (PMID 40867323, 2025). "Mutations in PIK3CA, which encodes for a catalytic subunit of phosphatidylinositol 3-kinase (PI3K), can be found in cases of atypical meningiomas and often co-occur with TRAF7 mutations, especially in cases of skull base meningiomas." (PMID 39202270, 2024). "In 2013, Clark and colleagues first described an association between WHO grade, histological subtype and the anatomical location of meningiomas with distinct molecular features, including mutations in TRAF7, KLF4, AKT1, SMO and NF2." (PMID 39273576, 2024). "Somatic mutations in TRAF7 are implicated in tumorigenesis, most reported for meningioma and mesothelioma." (PMID 38178633, 2024). "KLF4-K409Q mutations are found in a subset of NF2 wild-type meningiomas and almost always cooccur with mutations in TRAF7." (PMID 38571886, 2024). "TRAF7 mutations have been described in approximately 20–25% of all meningiomas and often co-occur with mutations in KLF4 or AKT1, which are in turn both mutually exclusive to each other." (PMID 39273576, 2024). "Particularly relevant to our studies of the Tri1:TRAF7 interaction are mutations within the TRAF7 WD40 domain associated with meningiomas." (PMID 38814079, 2024).
meningioma (continued). "Secretory meningiomas, a rare subtype associated with peritumoral edema, uniformly harbor co-mutation of TRAF7/KLF4." (PMID 38730704, 2024). "NF2 wild-type meningiomas frequently harbor mutations in TRAF7, KLF4, AKT1, PIK3CA, and SMO and are enriched in skull-base meningiomas." (PMID 38571886, 2024). "Monosomy, NF2 mutations, and TRAF7 mutations seem to be the drivers of tumorigenesis in sporadic meningiomas, and as many as 60% of all sporadic meningiomas involve a loss of heterozygosity on chromosome 22 due to inactivating mutations of NF2." (PMID 39796693, 2024). "Nearly a quarter of all meningiomas are characterized by TRAF7 loss, which is mutually exclusive with NF2 mutation." (PMID 39796693, 2024). "Further frequent non-NF2 driver mutations in meningiomas include oncogenic mutations in TRAF7, KLF4, AKT1 and SMO, which are all mutually exclusive to NF2 mutations." (PMID 39273576, 2024). "TRAF7 mutations are found in around 20–25% of meningiomas and most frequently occur in the C-terminal WD40 repeat domain." (PMID 38571886, 2024). "Additional frequent genomic alterations in meningioma include mutations in TNF receptor associated factor 7 (TRAF7), KLF transcription factor 4 (KLF4), and phosphatidylInositol-4,5-bisphosphate 3-kinase catalytic subunit alpha (PIK3CA)." (PMID 39726707, 2024). "Like TRAF7/KLF4-mutated meningiomas, also AKT1-mutated tumors are frequently found in the skull base." (PMID 36181606, 2023). "Krüppel-like factor 4(KLF4)/TNF receptor-associated factor 7(TRAF7) mutations can also be used to diagnose secretory meningiomas." (PMID 37529695, 2023). "TRAF7 mutations were found in approximately a quarter of all meningiomas in one study (72/300, 24%)." (PMID 36840836, 2023). "In agreement, TRAF7-deficient MEFs also had an increased expression of several investigated TRAF7 meningioma signature genes, including IL1RL1, KRT16, KRT6A, and AQP3." (PMID 36937440, 2023). "TRAF7 mutations occur in ~ 25% of meningiomas and seem to be mutually exclusive with NF2 mutations according to a genomic landmark study of 300 meningiomas." (PMID 36181606, 2023). "MC ben-1 meningiomas were enriched in NF2 mutations while the MC ben-2 subgroup was enriched in non-NF2 mutations including TRAF7, AKT1, KLF4, and SMO." (PMID 36840836, 2023). "The most frequent coding changes identified in non-NF2 meningiomas were missense mutations in TNF Receptor Associated Factor 7 (TRAF7), Kruppel-like factor 4 (KLF4), and RAC(Rho family)-alpha serine/threonine-protein kinase 1 (AKT1)." (PMID 36937440, 2023). "TRAF7 is mutated in about 20% of all meningiomas and is frequently associated with KLF4, AKT1, and PIK3CA mutations." (PMID 38137885, 2023). "In 2013, two separate landmark studies utilized whole genome and whole exome sequencing to uncover novel mutations in non-NF2 meningiomas including TRAF7 (TNF receptor associated factor 7), KLF4 (Krüppel-like factor 4), AKT1, and SMO (Smoothened)." (PMID 36840836, 2023). "In agreement with observed mutations in AKT1 and KLF4, TRAF7 meningiomas segregated into two distinct clusters." (PMID 36937440, 2023). "TRAF7 is the most common somatic mutation in non-NF2 meningiomas, present in ~ 25% of sporadic tumors." (PMID 34846640, 2022). "TRAF7 encodes for a ubiquitin E3 ligase and is the second most commonly mutated gene in meningiomas." (PMID 36686824, 2022). "Lastly, we detected FGF3 mRNA in primary human meningeal cells expressing KLF4K409Q and in human meningioma tumor specimens with a TRAF7/KLF4-mutated genotype." (PMID 35996584, 2022). "Among the six non-NF2 mutant subtypes, the TRAF7 mutated alone subtype is the most common in 25% of sporadic meningiomas and is associated with a higher grade." (PMID 36033542, 2022). "Conversely, a larger study on 3031 meningioma samples from 514 individual cases has shown that TRAF7, AKT1, and/or KLF4 mutations were significantly associated with a lower risk of progression." (PMID 35565385, 2022).
meningioma (continued). "A genomic study of 300 meningiomas showed mutations in TRAF7 in approximately 25% of all meningiomas, AKT1 mutations in 10-15% (affecting the PI3K signaling pathway) and KLF4 mutations in 10%." (PMID 36033542, 2022). "Recent data demonstrates that sphenoid wing meningiomas causing hyperostosis are associated with TRAF7 variants." (PMID 34846640, 2022). "One exception to this was a recurring co-mutation AKT1 and TRAF7 that occurred in higher grade meningiomas with a low-grade cytogenetic background." (PMID 35299730, 2022). "Meningiomas with TRAF7 pathogenic variants alone or in combination commonly develop in the skull base, with isolated TRAF7-mutated meningioma associated with a microcystic histological subtype." (PMID 33262459, 2021). "Mutations in TRAF7 have been identified in nearly one-fourth of meningiomas, while mutations in AKT1 and SMO have lower prevalence and are associated with higher grade NF2 wild-type tumors." (PMID 34300316, 2021). "PIK3CA mutations are found in 4–7% of meningiomas and often cooccur with TRAF7 mutations but are exclusive of NF2, AKT1, and SMO mutations." (PMID 33801089, 2021). "KLF4K409Q is the only mutation identified in the KLF4 gene associated with meningiomas, and like AKT1, it is commonly associated with TRAF7 co-mutation in meningiomas of the central skull base and sphenoid wings." (PMID 34638590, 2021). "ATK1 and PIK3CA are associated with the MTOR signaling pathway and act with TRAF7 in approximately 10–15% of all meningiomas and, interestingly, over 30% of all cancers." (PMID 34638590, 2021). "TRAF7 mutation predominantly contributed to improving the diagnosis, prognosis, and therapy of patients with meningiomas." (PMID 34775479, 2021). "TRAF7 mutations can also be found in meningiomas of the anterior skull base and middle cranial fossa in absence of any other oncogenes, suggesting an independent role or the presence of unidentified genetic drivers." (PMID 34638590, 2021). "Meningiomas with Krueppel-like-factor 4 (KLF4)/TNF receptor-associated factor 7 (TRAF7) mutation often locate in the medial skull base and v-akt murine thymoma viral oncogene homolog 1 (AKT1)/TRAF7 mutation in the anterior skull base." (PMID 33042832, 2020). "Tumors with KLF4 mutations are associated with larger peritumoral brain edema, localize to the anterior and middle cranial skull base, and when present with TRAF7 mutations are predictive of a secretory meningioma phenotype." (PMID 33346248, 2020). "For example, secretory meningiomas show frequent co-mutations of the KLF4 and TRAF7 genes, while clear cell meningiomas show SWI/SNF-related, matrix-associated, actin-dependent regulators of chromatin, subfamily e, member 1 (SMARCE1) mutations." (PMID 33014773, 2020). "The clinical significance of the mutations of NF2, KLF4, and TRAF7 were proven in meningiomas, and studies have shown a significant association between mutations and specific locations." (PMID 32974148, 2020). "TRAF7 mutations are present in approximately 25% of sporadic meningiomas, and studies have revealed they are mutually exclusive from NF2 mutant tumors, yet larger studies are need to confirm exclusivity of TRAF7 mutant tumors." (PMID 33346248, 2020). "Grade III meningioma are less likely to have TRAF7, AKT1, or SMO mutations, and exhibit genomic instability in the form of increased copy number variation." (PMID 32742192, 2020). "KLF4 mutations are nearly exclusively found in WHO grade 1 meningiomas and are often found with TRAF7 mutations." (PMID 33346248, 2020). "TRAF7 mutations were shown to be involved in genesis of human cancer, especially in about 25% of meningiomas, and de novo missense variants were also identified in ASD probands." (PMID 33362469, 2020). "As TRAF7 mutations were found in up to a quarter of meningiomas in prior studies, particularly in secretory meningiomas, such mutations would likely have been present in our matched tumor pairs." (PMID 31191822, 2019).
meningioma (continued). "The second most frequently mutated gene in meningiomas involves the tumor suppressor TNF receptor associated factor 7 (TRAF7) gene." (PMID 31470906, 2019). "At the genetic level, KLF4 is mutated in ~12% of grade I meningiomas, virtually all of which are of the secretory sub-type and also harbor TRAF7 mutations." (PMID 31970090, 2019). "KLF4 K409Q mutations were exclusively found in the presence of TRAF7 mutations and are commonly associated with secretory meningiomas." (PMID 31470906, 2019). "The pro-apoptotic E3 ubiquitin ligase, tumor necrosis factor receptor-associated factor 7 (TRAF7) is mutated ~24% of all meningiomas." (PMID 31970090, 2019). "These mutations are present in ~5.5% of grade I meningiomas, and are mutually exclusive with TRAF7, KLF4, and AKT1 mutations." (PMID 31970090, 2019). "Meningioma with TRAF7 mutations can harbor mutations in KLF4 or AKT1 in 40% and 33% of cases, respectively." (PMID 30082628, 2018). "In the non-NF2 meningiomas it was observed the frequent mutation of TRAF7, a proapoptotic ubiquitin ligase; a part of these meningiomas with mutated TRAF7 exhibited also KLF4 (a transcription factor involved in pluripotency) and AKT1 mutations." (PMID 30279357, 2018). "In meningioma, TRAF7 mutations can co-occur K409Q mutation in KLF4, a transcription factor known for its role in inducing pluripotency, and are mutually exclusive with NF2 mutations, chromosome 22 loss, and SMO mutations and was less common in HGMs." (PMID 30082628, 2018). "The tumor location changes according to the mutation type: anterior fossa, median middle fossa, or anterior calvarium for TRAF7/AKT1 and SMO mutated meningiomas; lateral middle fossa and median posterior fossa for TRAF7/KLF4-mutated meningiomas." (PMID 30279357, 2018). "Meningiomas with these alterations carry a significantly higher risk of being atypical as compared with non-NF2 meningiomas, including TRAF7 (with PI3K or KLF4 alterations), Hedgehog or POLR2A mutant tumours." (PMID 28195122, 2017). "Among these genes, TRAF7 was mutated most frequently among the high-grade meningiomas, but only in 10 of the 254 samples (4%)." (PMID 28713588, 2017). "For example, secretory meningiomas were driven exclusively by TRAF7/KLF4 co-mutations, while fibrous meningiomas were primarily associated with NF2 loss." (PMID 28195122, 2017). "As shown, three cases harbored TRAF7 mutations (the mutation sites are different from previously reported) and two known meningioma-driver mutations (AKT1E17K and SMARCB1R377H) were also detected." (PMID 28177878, 2017). "Mutations in SMO or AKT1/TRAF7 are most frequently observed in meningiomas of the anterior cranial base." (PMID 27458586, 2016). "It has been shown that KLF4 mutations were exclusive for secretory meningiomas so finding combined TRAF7/KLF4 mutation can serve in the diagnosis of secretory meningioma subtype." (PMID 27429002, 2016). "The most common of these is TRAF7, located on chromosome 16p13, which harbors a mutation in 12–25% of meningiomas." (PMID 27458586, 2016). "TRAF7 located on chromosome 16p13 is encoding a proapoptotic E3 ubiquitin ligase and the mutations of this gene occur in 24% of meningiomas." (PMID 27429002, 2016). "Recently it was reported that KLF4 K409Q together with TRAF7 mutations were harbored in most secretory meningioma patients." (PMID 27531889, 2016). "While TRAF7 mutations are usually de novo, there are some mutations that recur including missense mutations such as the Asn520 variant which has been reported more than 30 times in meningioma patients." (PMID 41372821, 2025). "Germline mutations in TRAF7 lead to the TRAF7 syndrome of developmental delay and other congenital anomalies, while somatic mutations drive tumor development including meningiomas, benign mesotheliomas, intraneural perineuriomas, and adenomatoid tumors of the genital tract." (PMID 41372821, 2025).